CXCR4 (C-X-C motif chemokine receptor 4)
Diseases named in the same sentence as CXCR4 in open-access papers (continued):
Sharing a sentence is not in itself a finding about the gene and the disease.
tumor (continued). "CXCR4 is an attractive target for cancer therapies due to its role in tumour growth, metastasis and shaping the tumour microenvironment." (PMID 40307933, 2025). "CXCR4 has been shown to interact with PI4KIIIα, a PI4K kinase, and through this interaction on lipid rafts it is able to mediate tumour metastasis, while PI3KIIIα knockouts inhibit CXCR4 mediated prostate cell metastasis." (PMID 39982274, 2025). "Studies have confirmed that CXCR4 is related to the proliferation, adhesion, invasion and metastasis of tumor cells, and plays an important role in tumor progression." (PMID 41347146, 2025). "In Mass’s study, infiltrating CXCR4+ neutrophils was identified as the primary source of S100A9 in the tumor microenvironment." (PMID 40069854, 2025). "The binding of Hypoxia-Responsive Elements (HRE) leads to the upregulation of the CXCR4 pathway, which promotes tumour development, migration, survival, and proliferation, and is associated with lung metastasis in clinical specimens." (PMID 41315643, 2025). "For example, transducing NK cells with CXCR4 or CXCR2 has enhanced their migration toward chemokine gradients produced by tumours, thereby improving in vivo tumour infiltration and efficacy." (PMID 40624498, 2025). "The resulting 64CuNOTA-CP01 exhibited CXCR4 specific tumour targeting for PET imaging, but still considerable liver accumulation." (PMID 40307933, 2025). "Inhibiting the tumor cell’s movement towards the CXCR4 prevents tumor cell migration and immune suppression and promotes the enhancement of the efficacy of chemotherapy and immunotherapy." (PMID 41383468, 2025). "High CXCL12 expression is associated with lymph node metastasis and poor survival, and the CXCL12/CXCR4 axis facilitates the recruitment of regulatory T-cells and M2 macrophages that support tumor immune escape." (PMID 40426863, 2025). "They include tumor heterogeneity, adaptive resistance mechanisms, as well as the complexity in the tumor microenvironment of CXCR4 signaling." (PMID 41383468, 2025). "Further, compared to the oe‐NC+M2pep‐Cs NPs/Plerixafor group, the expression of IFN‐γ, IL‐12, and IL‐6 was significantly reduced in the tumor tissues of mice in the oe‐CXCR4+M2pep‐Cs NPs/Plerixafor group." (PMID 40536774, 2025). "CXCL12, through interaction with CXCR4, regulates tumor cell survival, invasion, and immune suppression." (PMID 40426863, 2025). "POL5551 is a protein-epitope mimetic antagonist of CXCR4, designed to interfere with CXCL12–CXCR4 interactions involved in tumour metastasis and therapy resistance." (PMID 41002447, 2025). "Collectively, these data suggest that CXCR4 expression correlates to lower responsiveness to stimulation by tumor cells." (PMID 40155684, 2025). "In hypoxic microenvironmental conditions, malignant cells upregulate the expression of CXCR4, enhancing tumor growth, leukocyte migration, angiogenesis, and consequently, metastatic potential." (PMID 40142263, 2025). "On the other hand, the chemokine CXCL12 secreted by aHSCs can induce the quiescent state of NK cells through its homologous receptor CXCR4, thereby triggering the activation of tumor cells." (PMID 39966355, 2025). "In contrast, ERα signaling is linked to increased tumor invasion via MMP9 production, activation of the CXCL12/CXCR4 pathway and the promotion of M2 macrophage polarization and infiltration." (PMID 40612952, 2025). "Tumor-associated macrophages (TAMs), comprising up to 50% of the tumor mass, are recruited via chemokine axes such as CCL2/CCR2, CX3CL1/CX3CR1, and CXCL12/CXCR4 and adopt an M2-like immunosuppressive phenotype, facilitating immune escape and angiogenesis." (PMID 41002423, 2025). "Studies have shown that activation of the CXCL12/CXCR4 axis can inhibit T cell infiltration and function, promoting immune evasion by tumor cells." (PMID 41346595, 2025). "Tumor progression, migration, invasion, and angiogenesis through activation of CXCR4 signaling pathways." (PMID 40433410, 2025).
tumor (continued). "TGF-β signaling in the TME also promotes macrophage M2 polarization, and TGF-beta activates fibroblasts to form CAFs that secrete a higher level of CXCL12, which binds to the cognate receptor CXCR4 on M2 macrophages, leading to tumor cell growth." (PMID 40124621, 2025). "Utilizing targeted CXCR4 inhibitors mobilizes hematologic tumor cells from the bone marrow into peripheral circulation, enabling effective eradication by chemotherapy agents, small-molecule inhibitors, or demethylation agents." (PMID 40427609, 2025). "These nanofibers inhibit the CXCR4 signaling pathway, reducing tumor metastasis and improving T cell infiltration." (PMID 41155373, 2025). "CAFs promote CSC enrichment by activating the CXCL12/CXCR4 axis and increase the migratory ability and drug resistance of tumor cells by inducing EMT, further aggravating the malignant progression of tumors." (PMID 41346633, 2025). "Conversely, β-catenin and CXCR4 inhibitors suppressed tumor growth and downregulated Wnt signaling components." (PMID 40735647, 2025). "A critical prerequisite for the initiation of anti-cancer functions by stromal cells is their targeted homing to the tumor microenvironment, a process mediated by chemokine receptors including CXCR4, CXCR3, CCR4, CCR5, CCR7, and CCR9." (PMID 40784879, 2025). "High levels of CXCR4 expression correlate with poor prognosis and increased metastasis, as it directs tumor cells toward sites rich in its ligand, CXCL12." (PMID 40242222, 2025). "The debris from the TNBC cells provides antigen presentation and promotes enhanced anti-tumour immunity within the microenvironment by resolving the CXCR4/CXCL12-mediated immunosuppressive microenvironment and promoting tumour-specific immunity." (PMID 41002447, 2025). "A significant positive correlation between COX-2 and CXCR-4 expression was also observed, suggesting these markers’ role in tumor progression." (PMID 40959430, 2025). "MSCs migrate to tumor sites via the CXCR4/SDF-1 signaling axis and remodel the immunosuppressive microenvironment by secreting TNF-α and IL-1β, thereby enhancing PD-1 antibody delivery efficiency." (PMID 41301162, 2025). "Studies highlight the critical role of CXCR4 in chronic lymphocytic leukemia by facilitating tumor migration." (PMID 40607416, 2025). "Within the TME, CXCL12 and its receptor CXCR4 promote tumour angiogenesis, sustain tumour cell survival and proliferation, and orchestrate immunosuppressive responses." (PMID 40361472, 2025). "Preventing tumor cell migration, limiting metastatic burden, and enhancing anti-tumor immune activities to overcome resistance to standard therapies, blocking CXCR4 signaling is the way." (PMID 41383468, 2025). "Combination therapies represent an emerging and rational means by which to counteract the complex involvement of CXCR4/CXCL12 in tumour survival and metastasis, immune escape, and drug resistance." (PMID 41002447, 2025). "CXCR4 antagonists target CXCR4-upregulated tumor cells, block the CXCR4 receptor from binding to its ligand SDF-1 and inhibit bone and lung metastasis." (PMID 40075611, 2025). "The C-X-C motif chemokine receptor 4 (CXCR4) plays a critical role in cancer progression by facilitating tumor spread through angiogenesis, cell growth and immune response inhibition 1-6." (PMID 39776816, 2025). "Further optimization of Auristatin-conjugated anti-CXCR4 ADCs focused on lowering its affinity to preserve HSPCs while maintaining tumor-selective cytotoxicity." (PMID 40307933, 2025). "The CXCR4/CXCL12 axis certainly facilitates tumour cell homing, specifically in organs such as the lung, liver, bone, and lymph nodes, which are the most common sites of TNBC metastasis." (PMID 41002447, 2025). "Studies in preclinical models have demonstrated that plerixafor is a CXCR4 inhibitor that can reduce tumor cell migration, increase chemosensitivity, and re-establish immune response to limit metastasis and increase treatment efficacy." (PMID 41383468, 2025).
tumor (continued). "They secrete chemokines such as CXCL12, which activates the CXCR4 signaling axis and spatially confines immune cells to the tumor periphery." (PMID 41341574, 2025). "While increased recruitment of NK cells should logically be detrimental for tumor progression, we have shown that activation of CXCR4 and S1P1/5 additively inhibits NK cell activation." (PMID 40155684, 2025). "The MIF pathway, especially the MIF-CD74+CXCR4 pair, was identified as a critical contributor, consistent with its key role in tumor progression and metastasis." (PMID 41127012, 2025). "AMD3100, meanwhile, blocks the CXCL12/CXCR4 axis, preventing tumor cell migration and interaction with the stroma." (PMID 41348904, 2025). "It is a potent attractant for different cell types (immune, endothelial, and tumor cells), expressing its receptor, CXCR4." (PMID 40076892, 2025). "CXCR4 antagonists (e.g., plerixafor) modulate tumour microenvironment (TME) dynamics by disrupting the CXCR4/CXCL12 chemotactic axis, thereby impeding metastatic niche colonisation through interference with tumour cell tropism." (PMID 40411322, 2025). "The CXCL12 concentration gradient then drives the extravasation of CXCR4-positive tumor cells in circulation, leading to organ-specific metastasis." (PMID 40075611, 2025). "Meanwhile, CXCL12 can induce tumor cells to express CXCR4, promoting their metastasis to tissues with high CXCL12 expression, such as bone marrow and lymph nodes." (PMID 41346580, 2025). "Overall, as a CXCR4 antagonist, plerixafor influences tumor cells and the tumor microenvironment through multifaceted mechanisms, holding broad clinical prospects in OS applications." (PMID 40909292, 2025). "Targeting and blocking CXCR4 disrupts these processes, thereby blocking tumour progression, reducing resistance to chemotherapy, and supporting immunotherapies, making it a valuable focus in the development of anti-cancer strategies." (PMID 40307933, 2025). "On the other hand, by binding to CXCR4 on tumour cells and stroma, plerixafor antagonises CXCR4 signalling, blockading chemokine-mediated immunosuppressive cell recruitment while augmenting immune infiltrates." (PMID 41002447, 2025). "In parallel, groups treated with either CXCR4 inhibitor or IL-2 alone showed a marked inhibition of tumor proliferation compared to controls." (PMID 40698080, 2025). "CXCR4 has been established as a critical mediator in ccRCC progression, contributing to tumor growth and metastasis through multiple signaling pathways." (PMID 40396123, 2025). "Conversely, PDGF‐BB derived from tumours can further induce ECs to attract PCs through the SDF‐1α/CXCR4 axis and increase the barrier coverage of tumour vessels." (PMID 40268524, 2025). "By recruiting immunosuppressive cells such as Treg cells and M2 macrophages, the CXCL12/CXCR4 signaling pathway plays a critical role in tumor immune escape." (PMID 41376630, 2025). "Another key pathway is the CXCL12/CXCR4 axis, which is predominantly upregulated in hypoxic tumor regions." (PMID 41002423, 2025). "CXCR4 inhibition is also shown to increase tumor-infiltrating T cells and decrease immunosuppressive MDSCs in preclinical findings, and results in sensitization of tumors to the chemotherapy agents of cisplatin, paclitaxel, and gemcitabine." (PMID 41383468, 2025). "The chemokine receptor CXCR4 is recognized for facilitating the migration of tumor cells to bone and is commonly overexpressed in CTCs from patients with bone metastases." (PMID 40426987, 2025). "Spearman correlations between CXCR4 exosomal overexpression and circulating tumor cells (CTCs') phenotypes." (PMID 39575761, 2025). "Another target gene of HIF is CXCR4, a chemokine receptor that drives the migration of tumour cells to specific target organs, such as lung, liver or bone marrow, in response to its ligand CXCL12, making CXCR4 a key element in distant metastatic colonisation." (PMID 40869000, 2025).
tumor (continued). "CXC motif chemokine receptor 4 (CXCR4), a stromal cell-derived factor-1 receptor, was elevated in many tumour cells." (PMID 40433700, 2025). "The CXCL12/CXCR4 axis plays a crucial role in tumor‐stromal cell communication and creates a favorable microenvironment for tumor growth and recruitment of CXCR4+ tumor cells to CXCL12‐rich stromal niches to initiate metastasis." (PMID 40635521, 2025). "The inactivation of the CXCR4/PI3K/Akt/HIF-1 pathway played a pivotal role in mediating the capacity of erinacine S to inhibit chemoresistant CRC growth while enhancing tumor apoptosis." (PMID 41209562, 2025). "In most cancers, the abundance of the proinflammatory SELE+ vein subpopulation decreases as the tumour progresses, whereas the CXCR4+ proangiogenic tip cell subpopulation increases." (PMID 40268524, 2025). "Tumor cell homing, metastasis, and maintenance of cancer stem cells are all significantly regulated by CXCR4, which acts in part through interaction with the CXCL12 axis and co-opted in the signals from TGF β to increase invasiveness." (PMID 41348904, 2025). "For instance, CXCL12, secreted by tumor, stromal, and immune cells, binds to CXCR4, facilitating tumor growth, immune evasion, and therapy resistance." (PMID 40667699, 2025). "CXCR4 is a chemokine receptor that is frequently overexpressed in invasive breast cancer and plays a major role in tumor proliferation, aggressiveness and metastasis." (PMID 40075611, 2025). "Tumor cells frequently overexpress CXCL12, which binds to CXCR4 on neutrophils, directing their recruitment and facilitating interactions with tumor cells." (PMID 39940643, 2025). "CXCR4 antagonism, already validated for stem cell mobilization, demonstrates preclinical efficacy in blocking tumor cell bone homing through CXCL12-CXCR4 axis disruption." (PMID 40860192, 2025). "Additional immunohistochemistry staining demonstrated expression of CXCR4 within the tumour, in concordance to 68Ga‐pentixafor PET/CT findings." (PMID 39887860, 2025). "By disrupting ligand-induced CXCR4 signaling, these inhibitors impede downstream pathways involved in cytoskeletal remodeling, adhesion, and migration, thereby limiting tumor cell dissemination and metastatic colonization." (PMID 40552145, 2025). "C-X-C chemokine receptor type 4 (CXCR4) signaling regulates tumor cell proliferation, bone marrow metastasis, and resistance to chemotherapy." (PMID 40860200, 2025). "For example, expressing target tissue-specific receptors (such as tumor-highly expressed CXCR4 or CCR2) on the cell surface through genetic engineering can enhance its interaction with the lesion microenvironment." (PMID 40650096, 2025). "The enrichment of breast cancer CSCs through CXCL12/CXCR4 signalling is a contributor to prolonging tumour relapse and the propensity to metastasise post-treatment." (PMID 41002447, 2025). "The C-X-C chemokine receptor type 4 (CXCR4) has emerged as a key molecular biomarker for cancer therapies due to its critical role in tumor progression and metastases by displaying a stem cells phenotype." (PMID 40307933, 2025). "Originally identified as a co‐receptor for HIV‐1 in CD4+ T cell infection, CXCR4 expression has been detected in numerous cancer cells, often overexpressed at tumour sites alongside elevated stromal tissue CXCL12 levels." (PMID 39779470, 2025). "In drug loading, modified MSCs such as TRAIL, interleukin-10, microRNAs, or prodrug-converting enzymes can achieve precise localized release via CXCR4-mediated tumor-homing mechanisms." (PMID 41301162, 2025). "The CXCL12/CXCR4 axis plays a multifaceted role in tumor progression through interactions with stromal and immune components." (PMID 40607416, 2025). "Tumor cell proliferation was halted, and, critically, the influx of CXCR4+ monocytic MDSCs into the tumor was sharply reduced." (PMID 41583439, 2025).
tumor (continued). "The CXCL12-CXCR4 signaling axis is another key pathway through which CAFs mediate tumor progression, and blocking the interaction between CXCL12 and its receptor CXCR4 can exert anti-tumor effects." (PMID 40890855, 2025). "Our results demonstrated a significant reduction in both Tregs and CD8+ T cells within the tumor microenvironment following CXCR4 inhibitor treatment." (PMID 40698080, 2025). "During tumor development, tumor cells with high CXCR4 expression can spread or metastasize to tissues or organs with high CXCL12 expression through chemotaxis." (PMID 41413548, 2025). "Research by Li suggests that CXCR4 is overexpressed in tumor tissues compared to normal tissues, with its expression correlating with B cell and CD8+ cell infiltration." (PMID 40607416, 2025). "Plerixafor blocks CXCR4 and enables tumor cells to be mobilized from protective niches like the bone marrow and hypoxic tumor regions and making them more susceptible to therapeutic agents." (PMID 41383468, 2025). "Periodic pulsed administration of CXCR4 inhibitors, such as plerixafor, eradicates dormant tumor cells within the bone marrow niche." (PMID 41458551, 2025). "CXCR4+ cancer stem cells also show increased tumor invasion and cell migration, via the activation of Rac1 and MMP-2/MMP-14 proteinases and enhanced angiogenesis by triggering cancer cell adhesion to endothelial cells and upregulation of VEGF/VEGFR." (PMID 40307933, 2025). "AMD3465 has also been labelled with Cabon-11 as N-[11C]Methyl-AMD3465, showing good CXCR4 selectivity in a C6 glioma tumour model." (PMID 40307933, 2025). "Key chemokine receptors, such as CCR2, CCR6, CCL20 and CXCR4, have been identified as pivotal contributors to Treg recruitment at tumor sites." (PMID 41445742, 2025). "CXCR4-overexpressing cells induce tumor proliferation by overactivating the MAPK, PI3K/Akt and PLC signalling pathways." (PMID 40307933, 2025). "CXCR4 is overexpressed in more than 23 human cancers and contributes to tumour growth, invasion, and angiogenesis, thus making it an attractive and translationally promising molecular target." (PMID 39747850, 2025). "Through the pharmacological targeting of HIF-1 or the inhibition of CXCR4 with neutralizing antibodies, the influx of BMDCs was interrupted, contrasting tumor recovery." (PMID 40141406, 2025). "Overexpression of CXCL12 and CXCR4 in ACP promotes tumor cell proliferation, migration, and invasion, primarily via the activation of the PI3K/AKT signaling pathway." (PMID 40433410, 2025). "CXCR4 signaling recruits TAMs, MDSCs, and Tregs, collectively suppressing anti-tumor immunity and promoting therapy resistance." (PMID 41383468, 2025). "The binding of CXCR4 to its ligand CXCL12 activates the CXCL12/CXCR4 axis, which regulates tumor angiogenesis, promotes tumor metastasis, mediates immune dysfunction and plays a pivotal role in downstream cell-proliferation, migration and drug resistance." (PMID 40075611, 2025). "Further, tumor growth rates significantly accelerated in the oe‐CXCR4+M2pep‐Cs NPs/Plerixafor group relative to the oe‐NC+M2pep‐Cs NPs/Plerixafor group." (PMID 40536774, 2025). "In contrast, in the tumor tissues of mice in the oe‐CXCR4 group, the number of Th1 cells significantly decreased, whereas the number of Th2 cells significantly increased." (PMID 40536774, 2025). "In this study, we investigated the effects of CXCR4 antagonism on diverse blood vessels within the OSCC tumor stroma." (PMID 41210695, 2025). "For example, the CXCL12/CXCR4 axis promotes tumor proliferation, angiogenesis, and immune evasion by recruiting immunosuppressive cells such as regulatory T cells (Tregs) and myeloid‐derived suppressor cells (MDSCs)." (PMID 40145607, 2025). "The interaction that existed between MIF, its receptor CD74, and the chemokine receptor, CXCR4, is crucial in tumor biology, particularly cancer progression and metastasis." (PMID 40066443, 2025).